DHCR7 (7-dehydrocholesterol reductase)
Diseases named in the same sentence as DHCR7 in open-access papers (continued):
Sharing a sentence is not in itself a finding about the gene and the disease.
Alzheimer disease (3 papers, 2017 to 2022). A progressive, neurodegenerative disease characterized by loss of function and death of nerve cells in several areas of the brain leading to loss of cognitive function such as memory and language. "Findings:DHCR7 rs12785878 T>C was found to be significantly associated with an increased risk of early-onset Alzheimer's disease (EOAD) (n = 300, risk allele C, adjusted OR = 1.542, adjusted 95% CI = 1.176–2.023, p = 0.002)." (PMID 33692822, 2021). "The polymorphisms of DHCR7/NADSYN1 participate in susceptibility to many diseases, including deficiency of VitD, acute coronary syndrome, Alzheimer’s disease and ULs." (PMID 35795205, 2022).
bladder cancer (3 papers, 2023 to 2025). "For example, DHCR7 overexpression correlates with poor prognosis in cervical, gastric, breast, and bladder cancers, while loss‐of‐function mutations (e.g., rs104886035/rs104886038) disrupt cholesterol metabolism to suppress tumor growth." (PMID 41198144, 2025). "Similarly, in bladder cancer tissues, the upregulation of DHCR7 expression is induced by m6A modification, which changes mRNA stability and translational efficiency." (PMID 40427562, 2025).
colorectal cancer (3 papers, 2023 to 2025). A primary or metastatic malignant neoplasm that affects the colon or rectum. "TASINs were found to inhibit EBP, DHCR7, and DHCR24, leading to colorectal cancer cell death." (PMID 38672427, 2024).
diabetes (3 papers, 2018 to 2022). "DHCR7 affects the Hedgehog signaling pathway and the production of vitamin D3; it also participates in lipid metabolism, the occurrence of diabetes and the formation of insulin resistance." (PMID 36712880, 2022). "The effects on risk of diabetes were assessed by a genetic score using two 25(OH)D synthesis SNPs (DHCR7-rs12785878 and CYP2R1-rs10741657), with and without the addition of SNPs affecting the transport (GC/DBP-rs2282679) and catabolism (CYP24A1-rs6013897) of 25(OH)D." (PMID 29718904, 2018).
glioma (3 papers, 2023 to 2025). A benign or malignant brain and spinal cord tumor that arises from glial cells (astrocytes, oligodendrocytes, ependymal cells). "Interestingly, vitamin D3 obtained more significant inhibitory effects on cell viability and cell proliferation of patient‐derived glioma cell lines by inhibiting the expression levels of DHCR7 and DHCR24, thereby inhibiting cholesterol synthesis and cholesterol homeostasis pathways." (PMID 37489660, 2023). "Additionally, it was shown in human glioma cell lines that vitamin D3 but not 1,25(OH)D inhibits the expression of DHCR7, which leads to the inhibition of cholesterol synthesis and the accumulation of 7-DHC and other sterol intermediates." (PMID 38933885, 2024).
thyroid cancer (3 papers, 2019 to 2026). "The DHCR7 rs12785878 minor allele was associated with thyroid cancer under an additive (OR 1.38, 95% CI 1.15–1.65, p = 0.0004) and codominant (OR 1.88, 95% CI 1.30–2.74, p = 0.0021) model." (PMID 31357732, 2019). "In conclusion, our data suggest that DHCR7 rs12785878 is a novel risk locus for thyroid cancer and that CYP2R1 rs2060793 may confer a protective effect against disease progression." (PMID 31357732, 2019). "Some associations between thyroid cancer risk (VDR, CYP24A1, DHCR7) or the clinical course of the disease (VDR) and vitamin D-related gene polymorphisms were described in the literature." (PMID 36362448, 2022). "The aim of this study was to determine if the DHCR7 rs12785878, CYP2R1 rs2060793, and CYP24A1 rs6013897 SNPs are also associated with susceptibility to thyroid cancer." (PMID 31357732, 2019). "Downregulation of RTN3 lead to stabilization of DHCR7 and elevate cholesterol concentration, activating EGFR/ERK pathway and contributes to progression of thyroid cancer, which can be rescued by HMG-CoA reductase inhibitor Simvastatin." (PMID 41813657, 2026).
asthma (2 papers, 2017 to 2020). "To assess the effect of the independent vitamin D pathways on risk of asthma, we analyzed SNPs near genes implicated in 25OHD synthesis (DHCR7 and CYP2R1) and metabolism (GC and CYP24A1) separately and found that none were associated with increased risk of asthma." (PMID 28486474, 2017).
autoimmune disease (2 papers, 2012 to 2020). A disorder resulting from loss of function or tissue destruction of an organ or multiple organs, arising from humoral or cellular immune responses of the individual to their own tissue constituents. "This set of SLE-associated genes includes DHCR7 and NADSYN1, enzymes involved in the biogenesis of vitamin D, a process known to play an important role in autoimmune disease susceptibility." (PMID 32620744, 2020).
ciliopathies (2 papers, 2020 to 2021). "Postaxial polydactyly is often noted in SRP and finger abnormalities are found in association with ciliopathies and DHCR7 mutations, suggesting that cholesterol processing was needed for the correct patterning of fingers." (PMID 34576017, 2021).
cleft palate (2 papers, 2016 to 2024). Cleft palate is a fissure type embryopathy that affects the soft and hard palate to varying degrees. "In the setting of Dhcr7 dysfunction, the catalytic synthesis of endogenous cholesterol cannot meet the needs for normal palate fusion, leading to the occurrence of cleft palate." (PMID 27066502, 2016). "It should be noted that, in this study, we analyzed Dhcr7 KO mice without cleft palate." (PMID 38438535, 2024).
Cognitive impairment (2 papers, 2016 to 2022). Abnormal cognition is characterized by deficits in thinking, reasoning, or remembering. "Impaired DHCR7 function is associated with a spectrum of congenital malformations, intellectual impairment, epileptiform activity and autism spectrum disorder." (PMID 26685159, 2016).
Hepatic steatosis (2 papers, 2024 to 2025). Steatosis is a term used to denote lipid accumulation within hepatocytes. "H&E analysis of liver tissues revealed that hepatic steatosis was strongly suppressed (↓2.5-fold) in HFD + EtOH-fed Dhcr7+/– mice." (PMID 40529212, 2025). "Remarkably, Dhcr7+/– mice were protected from alcohol-induced hepatic steatosis, inflammation, fibrosis, and HCC (vs. WT mice)." (PMID 40529212, 2025). "Our findings identified that the upregulation of DHCR7 contributes to the pathogenesis of MetALD and its inhibition suppresses hepatic steatosis, inflammation, fibrosis, and tumor proliferation." (PMID 40529212, 2025). "Here we evaluated the role of DHCR7 in the pathogenesis of MetALD and HCC in alcohol-injured wild-type (WT) and Dhcr7+/– mice and determined that suppression of DHCR7 ameliorates hepatic steatosis, inflammation, and fibrosis and reduces the incidences of alcohol-induced HCC." (PMID 40529212, 2025). "In an experimental ASH model, genetic ablation of the IL-17RA in steatotic hepatocytes downregulated TNFRI, sterol regulatory element-binding proteins 1/2 (SREBP1/2), and 7-dehydrocholesterol reductase (DHCR7), leading to protection against hepatic steatosis and HCC development." (PMID 39156888, 2024).
hypovitaminosis D (2 papers, 2013 to 2019). "In this study, the association of GC, CYP2R1, and DHCR7/NADSYN1 polymorphisms with vitamin D deficient rickets in Chinese subjects was reported for the first time." (PMID 24073854, 2013). "This study aimed to investigate the association between GC, CYP2R1, and DHCR7/NADSYN1 and rickets in northeastern Han Chinese children." (PMID 24073854, 2013). "However, our study found little evidence that DHCR7/NADSYN1 variants were associated with a genetic risk of rickets." (PMID 24073854, 2013).
lathosterolosis (2 papers, 2019 to 2021). Lathosterolosis is an extremely rare inborn error of sterol biosynthesis characterized by facial dysmorphism, congenital anomalies (including limb and kidney anomalies), failure to thrive, developmental delay and liver disease. "Mutations in Dhcr7 and Sc5d, which encode enzymes that catalyze the terminal steps in cholesterol biosynthesis, impair HH signaling in target cells and cause the congenital malformation syndromes Smith-Lemli-Opitz and lathosterolosis, respectively." (PMID 31657721, 2019).
liver cancer (2 papers, 2024 to 2025). An epithelial or non-epithelial malignant neoplasm that arises from the liver. "Future studies will elucidate the contribution of DHCR7-cholesterol synthesis across different types of liver cancer and investigate the therapeutic efficacy of DHCR7 inhibitors administered in combination with other treatments." (PMID 40529212, 2025). "Indeed, we confirmed that the DHCR7 expression in Huh-7 cells is much higher than that in other ferroptosis-sensitive cancer cells, including liver cancer." (PMID 38472233, 2024).
pancreatic cancer (2 papers, 2015 to 2023). "For example, in pancreatic cancer, high DHCR7 gene expression results in shorter survival of patients." (PMID 37759721, 2023).
schizophrenia (2 papers, 2020 to 2024). A major psychotic disorder characterized by abnormalities in the perception or expression of reality. "For instance, maternal exposure to aripiprazole (ARI), used to treat patients with schizophrenia and bipolar disorders, inhibits the 7-dehydrocholesterol reductase (DHCR7), the last enzyme in cholesterol biosynthesis." (PMID 32722471, 2020).
acute liver failure (1 paper, 2024). Rapid deterioration of liver function causing encephalopathy and coagulopathy. "We further show that AY9944 inhibits hepatic ischemia-reperfusion injury, and genetic ablation of Dhcr7 prevents acetaminophen-induced acute liver failure in mice." (PMID 38472233, 2024). "To further evaluate the suppressive effects of DHCR7 inhibition on hepatic ferroptosis in vivo, we examined whether genetic ablation of Dhcr7 could prevent APAP-induced acute liver failure, another mouse model of ferroptosis-related liver injury accompanied by lipid peroxidation." (PMID 38472233, 2024).
Anxiety (1 paper, 2025). Intense feelings of nervousness, tension, or panic often arise in response to interpersonal stresses. "DHCR7-deficient zebrafish have been shown to be hyperactive, expressing behaviors of reduced fear and anxiety in their surroundings." (PMID 40700140, 2025).
bacterial sepsis (1 paper, 2020).
Becker muscular dystrophy (1 paper, 2025). Becker muscular dystrophy (BMD) is a neuromuscular disease characterized by progressive muscle wasting and weakness due to degeneration of skeletal, smooth and cardiac muscle. "In 5 couples, both partners have P/LP variants in the same AR gene (CFTR, GJB2, ATP7B, DHCR7), and in one couple, a woman has a clinically significant variant in the DMD gene linked to Becker muscular dystrophy." (PMID 41595422, 2025).
Behçet’s disease (1 paper, 2016). "Recently polymorphisms in Vitamin D receptor (VDR) and 7-dehydrocholesterol reductase (DHCR7) genes have been associated with Behçet’s disease." (PMID 27716192, 2016).
bladder urothelial carcinomas (1 paper, 2025). "Importantly, DHCR7 demonstrates strong potential as a prognostic biomarker, particularly in bladder urothelial carcinoma, with broader implications for other malignancies." (PMID 41198144, 2025). "Additionally, DHCR7 expression demonstrated significant correlations with the regulation of several markers of T helper cells (Th1, Th2, Tfh, and Th17) in the four bladder urothelial carcinomas." (PMID 41198144, 2025).
Burkitt lymphoma (1 paper, 2025). A rare form of malignant mature B-cell non-Hodgkin lymphoma. "In Burkitt lymphoma (BL), 7-dehydrocholesterol reductase (DHCR7) and its substrate 7-dehydrocholesterol (7-DHC) have been implicated in ferroptosis regulation." (PMID 41462004, 2025).
cholangiocarcinoma (1 paper, 2025). A carcinoma that arises from the intrahepatic biliary tree (intrahepatic cholangiocarcinoma) or from the junction, or adjacent to the junction, of the right and left hepatic ducts (hilar cholangiocarcinoma). "Conversely, DHCR7 mRNA expression was low in CHOL (cholangiocarcinoma), KIRC (kidney renal clear cell carcinoma), KIRP (kidney renal papillary carcinoma), and PCPG (pheochromocytoma and paraganglioma)." (PMID 41198144, 2025).
chronic hepatitis C (1 paper, 2013). "Associations between CYP2R1, GC, and DHCR7 genotypes that are determinants of reduced 25-hydroxyvitamin D (25[OH]D3) serum levels and the risk of HCV-related HCC development were investigated for 1279 chronic hepatitis C patients with HCC and 4325 without HCC, respectively." (PMID 23734184, 2013).
Cirrhosis (1 paper, 2018). A chronic disorder of the liver in which liver tissue becomes scarred and is partially replaced by regenerative nodules and fibrotic tissue resulting in loss of liver function. "However, three of these genes (DHCR7, IFN‐g, IL‐10) had additional evidence of an association with cirrhosis or fibrosis." (PMID 29397014, 2018).
Frasier syndrome (1 paper, 2021). Frasier syndrome is characterized by the association of male pseudohermaphrodism and glomerular nephropathy. "However, the phenotype of the patient did not fit the Smith–Lemli–Opitz syndrome (MIM 270400) or 46,XY Frasier Syndrome (MIM 136680), which are associated with DHCR7 and FREM2, respectively." (PMID 34943163, 2021).
Glioblastoma multiforme (1 paper, 2025). "Our study revealed that lactylation risk score associated DHCR7 knockdown enhances the response to BLCA immunotherapy, aligning closely with findings from a recent study in Glioblastoma multiforme." (PMID 40735323, 2025).
Hypocholesterolemia (1 paper, 2025). An decreased concentration of cholesterol in the blood. "AY9944 inhibits the enzymatic activity of DHCR7, causing hypocholesterolemia." (PMID 40529212, 2025).
invasive ductal carcinoma (1 paper, 2020). "The feature plots and spatial feature plots were utilized to illustrate the distribution and expression of CIRBP, FAM110B, ACAA1, ACAT1, and DHCR7, showing that these key genes were highly expressed in the invasive ductal carcinoma tissue (cluster 2, 5, 8)." (PMID 32984314, 2020).
lepromatous leprosy (1 paper, 2021). A chronic communicable infection which is a principal or polar form of leprosy. "Furthermore, we observed a prominent upregulation toward higher MOI (100:1) when genes associated with cholesterol and fatty acid metabolism (DHCR7, MVK, and MSMO, and LACC1/FAMIN were analyzed, which are pathways involved in lepromatous leprosy immunopathogenesis." (PMID 33936067, 2021).
leukemia (1 paper, 2011). A malignant (clonal) hematologic disorder, involving hematopoietic stem cells and characterized by the presence of primitive or atypical myeloid or lymphoid cells in the bone marrow and the blood. "Remaining candidates (N = 62) comprised BDNF-related genes (SST), MAPK-pathway genes (KRAS, IGF1R, GNG11 and RAP1A), genes related with leukemia (SFRP1) and Rho-Proteins (DHCR7 and RAB21)." (PMID 21569303, 2011).
leukopenia (1 paper, 2021). "Moreover, several SNPs in CYP27A1, GC, and DHCR7 genes were related to multiple clinical features, including leukopenia, drug resistance, pulmonary infection, fever, and DILI, in PTB patients." (PMID 33882819, 2021).
liver diseases (1 paper, 2024). "Our findings reveal a regulatory mechanism of hepatic ferroptosis and highlight DHCR7 and 7-DHC as potential therapeutic targets for ferroptosis-related liver diseases." (PMID 38472233, 2024).
lung adenocarcinoma (1 paper, 2025). A carcinoma that arises from the lung and is characterized by the presence of malignant glandular epithelial cells. "High DHCR7 expression was associated with consistently worse survival across seven lung adenocarcinoma datasets." (PMID 41246332, 2025).
lymphoma (1 paper, 2025). A malignant (clonal) proliferation of B- lymphocytes or T- lymphocytes which involves the lymph nodes, bone marrow and/or extranodal sites. "In lymphoma, 7-Dehydrocholesterol, an endogenous metabolite, enhances the survival ability of lymphoma cells by protecting their lipids from peroxidation and reducing their sensitivity to ferroptosis, especially for DHCR7-mutated Burkitt lymphoma." (PMID 40093329, 2025).
Micro syndrome (1 paper, 2023). "Pathogenic variants in the 7-dehydrocholesterol reductase gene, DHCR7, cause Smith–Lemli–Opitz syndrome, which has a similar spectrum of features and is among the top differential diagnoses for Micro syndrome." (PMID 37774976, 2023).
Neonatal sepsis (1 paper, 2020). Systemic inflammatory response to infection in newborn babies.
non-alcoholic fatty liver disease (1 paper, 2024). "Additionally, CYP2R1 and DHCR7 are related to vitamin D metabolism, LIPA is associated with non-alcoholic fatty liver disease, and CYP21A1 affects animal development." (PMID 39376613, 2024).
Osteopenia (1 paper, 2018). Osteopenia is a term to define bone density that is not normal but also not as low as osteoporosis. "A statistically significant association was observed for the variants rs3794060 and rs4944957 of the DHCR7/NADSYN1 gene with osteopenia/osteoporosis." (PMID 30150596, 2018). "Moreover, an association was observed for the variants rs3794060 and rs4944957 of the DHCR7/NADSYN1 gene with osteopenia/osteoporosis." (PMID 30150596, 2018). "However, an association of the NADSYN1/DHCR7 gene with osteopenia/osteoporosis was identified." (PMID 30150596, 2018).
parasitemia (1 paper, 2022). "Except for DHCR7, which negatively correlated with high parasitemia, transcription profiles of immunoregulatory genes differentially expressed between asymptomatic infected individuals and healthy controls were not correlated with parasitemia levels." (PMID 35475529, 2022).
polycystic kidney (1 paper, 2025). "Notably, patients with Smith–Lemli–Opitz syndrome, which is caused by germline mutations in the DHCR7 gene encoding the last enzyme in the de novo cholesterol synthesis pathway, show polycystic kidney." (PMID 39900437, 2025).
ptosis (1 paper, 2025). The drooping of the upper eyelid. "Dhcr7(-/-) mouse models demonstrate that 7-DHC supports Ret signaling, but its deficiency impairs cholesterol synthesis, potentially compromising sympathetic nervous system function through disrupted Ret signaling pathways and inducing ptosis." (PMID 41049435, 2025).
renal cell carcinoma (1 paper, 2025). "We observed that DHCR7 knockdown significantly suppressed renal cell carcinoma cell proliferation." (PMID 41198144, 2025). "DHCR7‐knockdown can inhibit cell growth and proliferation in renal cell carcinoma." (PMID 41198144, 2025). "To determine whether DHCR7 is essential for cancer cell growth, we performed genetic knockdown of DHCR7 in a panel of human renal cell carcinoma cell lines using an shRNA system, and examined the effects of DHCR7 knockdown on the proliferation and viability of renal cell carcinoma cells." (PMID 41198144, 2025).
Respiratory insufficiency (1 paper, 2007). "Severe cholesterol deficiency, caused by the intentional genetic ablation of Dhcr7 in the mouse, has proven to be incompatible with perinatal life and is associated with respiratory insufficiency after birth." (PMID 17408495, 2007). "One cause of early postnatal death in the Dhcr7 null animals appears to be associated with anoxia due to diffuse atelectasis of the late gestational lungs, which may cause immature formation of gas-exchange unit and subsequent respiratory insufficiency after birth." (PMID 17408495, 2007).
retinal degeneration (1 paper, 2018). Degeneration of the retina. "A rat model of the disease has been created by treating normal rats with the DHCR7 inhibitor, AY9944, which causes progressive, irreversible retinal degeneration." (PMID 30360379, 2018).